ELAVL1 (ELAV like RNA binding protein 1)
Diseases named in the same sentence as ELAVL1 in open-access papers (continued):
Sharing a sentence is not in itself a finding about the gene and the disease.
hepatocellular carcinoma (62 papers, 2011 to 2025). A malignant tumor that arises from hepatocytes. "The reader protein YBX1 recognizes m5C-modified mRNA and recruits ELAVL1 to stabilize hepatoma-derived growth factor mRNA, thus facilitating bladder cancer cell growth and metastasis." (PMID 39164641, 2024). "In human hepatocellular carcinoma cells, ELAVL1 regulates both autophagosome formation and autophagic flux via mediating translation of the autophagy-related genes (ATGs) ATG5 and ATG12." (PMID 38373797, 2024). "For example, circRHOBTB3 is expressed at relatively low levels in hepatocellular carcinoma, and it has been reported that over-expression of circRHOBTB3 can lead to degradation of ELAVL1 and thus inhibition of the expression of the ELAVL1 target gene PTBP1." (PMID 35465324, 2022). "In another regulatory mechanism, direct binding of Hsa_circ_00074854 to the ELAVL1 protein improves the stability of the protein, and ultimately promotes hepatocellular carcinoma migration, invasion and epithelial-mesenchymal transition." (PMID 35465324, 2022). "On another hand, ELAVL1 binds pre-miRNA-199a to prevent its maturation, leading to enhanced glycolytic metabolism in hepatocellular carcinoma cells in response to hypoxia." (PMID 35465324, 2022). "Similarly, hsa_circ_0074854 promotes the migration and invasion of hepatocellular carcinoma cells by stabilizing ELAVL1." (PMID 35465324, 2022). "Evidence for this scenario was documented when the lncRNA-UFC1 could directly interact with ELAVL1 in hepatocellular carcinoma cells." (PMID 27102850, 2016). "In hepatocellular carcinoma cells, the highly expressed lincRNA-UFC1 directly binds to ELAVL1, leading to an increase of β-catenin mRNA and protein and finally increased cell proliferation and decreased apoptosis." (PMID 35465324, 2022). "It has been reported that ELAVL1 can suppress the expression of HK2 and pyruvate kinase-M2 (PKM2) by specifically binding to miR-199a precursor, consequently promoting the proliferation and growth of hepatocellular carcinoma." (PMID 39390359, 2024). "Importantly, the expressional changes of some RBPs, including HuR (ELAVL1) and PTBP1, are aberrantly expressed and co-related with the prognosis of ovarian and hepatocellular carcinoma patients." (PMID 34202873, 2021).
lung cancer (61 papers, 2013 to 2025). A malignant neoplasm involving the lung. "For example, ELAVL1 exhibited specific activity in lung cancer cells, which has been found to play critical roles in lung cancer." (PMID 36681772, 2023). "ELAVL1 can inhibit ferroptosis in lung cancer cells, and ELAVL1 itself also promotes this process by stabilizing LINC00336 transcription." (PMID 35784729, 2022). "For example, upregulation of the lncRNA, LINC00336, in lung cancer cells has been shown to activate the LSH/ELAVL1/LINC00336 axis, resulting in inhibition of ferroptosis and increased tumor formation." (PMID 35359880, 2022). "It is unveiled that LINC00336 accelerated tumor formation and inhibited ferroptosis of lung cancer through the LSH/ELAVL1/LINC00336 axis." (PMID 35127813, 2021). "LINC00336, a type of lincRNA with large intergenic transcripts that cover over 200 nt, has been reported to enhance proliferation of lung cancer cells and inhibit ferroptosis through an ELAVL1-dependent manner." (PMID 34235152, 2021). "ELAVL1 is overexpressed in lung cancer and regulates cell proliferation and survival, and miR-519 directly modulates HuR expression." (PMID 30787392, 2019). "Moreover, the oncogene LINC00336 was found to inhibit ferroptosis by interacting with ELAVL1 in lung cancer." (PMID 38169402, 2024). "Moreover, ELAVL1 directly stabilizes LINC00336 in lung cancer cells." (PMID 35382824, 2022). "This study revealed that m6A‐related genes significantly contribute to lung cancer, with the expression levels of YTHDF1, YTHDF2, ELAVL1 and ZC3H13 being crucial for predicting and treating lung cancer, providing new therapeutic targets." (PMID 39135292, 2024). "So FOXD3-AS1 in exosomes derived from lung cancer cells can upregulate the expression of ELAVL1 and activate the PI3K/Akt pathway to promote lung cancer progression and resistance to 5-FU, providing a new strategy for the treatment of lung cancer." (PMID 39705424, 2024). "Exosomes derived from lung cancer cells can promote the proliferation and invasion of A549 cells, inhibit 5-FU induced apoptosis, and transfection of si-FOXD3-AS1 or si-ELAVL1 into A549 cells cultured with exosomes can reverse these effects." (PMID 39705424, 2024). "For example, ZC3H13, CBLL1, ELAVL1, and YTHDF1 are differentially expressed in lung cancer tissues, which is significant for predicting and treating lung cancer." (PMID 37938417, 2023). "We then detected ELAVL1 protein levels in ten lung cancer cases (five cases for ADC and five cases for SCC) and observed that ELAVL1 protein levels increased in lung cancer tissues." (PMID 30787392, 2019). "The lncRNA LINC00336 may increase the growth of lung cancer cells through the LSH/ELAVL1/LINC00336 axis, accelerate tumor formation, and inhibit ferroptosis pathways in lung cancer cells." (PMID 35756659, 2022). "Given that ELAVL1 binds to many mRNAs, and that LINC00336 is highly expressed in lung cancer, we hypothesized that ELAVL1 may influence the posttranscriptional levels of interacting genes, including LINC00336." (PMID 30787392, 2019). "In addition, overexpressed LINC00336 acted as a crucial ferroptosis inhibitor in lung cancer by lowering cellular iron, lipid peroxidation, and mitochondrial superoxide through ELAV-like RNA-binding protein 1 (ELAVL1) interactivity, a novel regulator of ferroptosis." (PMID 35813823, 2022). "Finally, we further analyzed the correlation between ELAVL1 and LINC00336 in lung cancer." (PMID 30787392, 2019).
colon carcinoma (56 papers, 2012 to 2025). "Immunohistochemical analysis of paired tumor and healthy tissues revealed that ELAVL1 expression and cytoplasmic abundance positively correlated with tumor malignancy and advanced tumor stage, especially in colon cancer." (PMID 36324584, 2022). "According to the colon cancer Cox regression test and Kaplan–Meier (K-M) curves of key genetic risk factors, the five most significant genes selected were: ELAV-like RNA-binding protein 1 (ELAVL1), GPX2, EPAS1, SLC7A5, and high mobility group box 1 (HMGB1)." (PMID 36324584, 2022). "However, it is worth noting that the increased expression of ELAVL1 is identified to promote the overexpression of COX-2, and thus contributing to the growth of colon cancer, whose risk is increased in the setting of CD." (PMID 32724827, 2020). "Our results suggest that five core genes, ELAVL1, GPX2, EPAS1, SLC7A5, and HMGB1, are involved in the ferroptosis of colon cancer cells." (PMID 36324584, 2022). "We identified five core genes, ELAVL1, GPX2, EPAS1, SLC7A5, and HMGB1, involved in the ferroptosis of colon cancer." (PMID 36324584, 2022).
pancreatic cancer (53 papers, 2010 to 2026). "ELAVL1 is also present in this functional node, and it has been associated with response to gemcitabine in pancreatic cancer." (PMID 35626021, 2022). "Additionally, ELAVL1 has been implicated in the development of resistance to cancer therapies in several malignancies, including PCa, pancreatic cancer, oral cancer, and colorectal cancer." (PMID 40958880, 2025). "Numerous studies have shown that ELAVL1 is overexpressed in a range of cancers, including lung, liver, and pancreatic cancers, where it promotes tumorigenesis by stabilizing the mRNAs of cancer-related genes." (PMID 40958880, 2025). "In particular, it has been reported that ELAVL1 interacts with AHR mRNA to increase gemcitabine sensitivity in pancreatic cancer cells." (PMID 39588852, 2025). "ELAVL1 is an important RNA-binding protein that has been shown to be highly expressed in various cancers, including lung cancer, liver cancer, and pancreatic cancer, where it significantly promotes tumorigenesis and progression." (PMID 40958880, 2025). "Overexpression of ELAVL1 in pancreatic cancer cells has been shown to increase the sensitivity of patients to gemcitabine treatment." (PMID 35465324, 2022). "In another report, ELAVL1 was also shown to be involved in the apoptosis of pancreatic cancer cells exposed to gemcitabine." (PMID 35465324, 2022). "In pancreatic cancer, ELAVL1 was shown to regulate apoptosis through the IAP1 and IAP2 proteins." (PMID 37685961, 2023). "The role of ELAVL1 in pancreatic cancer remain controversial." (PMID 35465324, 2022). "Other RBPs with suggested tumor-promoting roles in PDAC include the 5’-3’ exonuclease EXO1 and the RBPs HuR (ELAVL1) and PTBP3, which both have been reported to lead to hypoxia-induced chemoresistance in pancreatic cancer cells." (PMID 32545414, 2020). "In addition, ELAVL1 has also been described as an EMT modulator in breast and pancreatic cancers." (PMID 37298909, 2023).
ovarian carcinoma (46 papers, 2012 to 2025). A malignant neoplasm originating from the surface ovarian epithelium. "Downregulated genes in G1 condition were mainly associated with ovarian cancer tumors and xenografts down (dn), ELAVL1 targets up, liver cancer ciprofibrate up, liver cancer E2F1 up, liver cancer ACOX1 up, and SATB1 targets dn." (PMID 41479593, 2025). "These differential associations between TUBB3, ELAVL1, and miR-200c may clarify the differences in the chemotherapy treatment outcomes particularly in the action of miR-200c in ovarian cancer." (PMID 27601996, 2016). "It has been reported that ELAVL1 interacts with TIMM44 mRNA to regulate its stability in ovarian cancer." (PMID 38394156, 2024). "Accordingly, it has been found that levels of ELAVL1 in the cytoplasm of cells in ovarian cancer tissues was significantly increased relative to levels in borderline tumors or normal ovaries." (PMID 35465324, 2022). "In the third type of regulation, up-regulated FAM83H-AS1 binds to ELAVL1 and stabilizes it, which can induce cell metastasis and resistance to radiotherapy in ovarian cancer." (PMID 35465324, 2022). "Given its regulatory function on a subset of transcripts involved in malignant transformation and cell proliferation, several studies proposed a central role of ELAVL1 in breast, colon, lung and ovarian cancer." (PMID 24417896, 2014). "Furthermore, ELAVL1 has been researched as a therapeutic target for various other cancers, such as colorectal, breast, and ovarian cancers." (PMID 34681774, 2021). "Simultaneously, to understand the biology behind the key signatures, the protein expression of ALKBH5, WTAP, ELAVL1, and CDH2 in ovarian cancer was analyzed using CPTAC datasets." (PMID 37684273, 2023). "CDH2, ALKBH5, ELAVL1, and WTAP are the key regulators that exert a critical impact on the development and prognosis of ovarian cancer." (PMID 37684273, 2023). "Subsequently, we used the ssGSEA algorithm and overall survival analyses to identify the key prognosis-related immunological signatures in ovarian cancer, which included WTAP, ELAVL1, CDH2, and ALKBH5." (PMID 37684273, 2023). "Next, utilizing the ssGSEA algorithm and conducting overall survival analyses, we have identified the key prognosis-related immunological signatures in ovarian cancer to be ALKBH5, WTAP, ELAVL1, and CDH2 as the regulators." (PMID 37684273, 2023). "Another interaction with ovarian cancer involves miR-519, which targets the 3′-UTR of ELAVL1 mRNA, inhibiting its translation and slowing cell division of A2780 cells, a human ovarian cancer cell line, in vitro." (PMID 35465324, 2022). "Additionally, significant correlations were observed between the methylation of ALKBH5, WTAP, ELAVL1, CDH2 and immunoinhibitors, immunostimulators, and MHC molecules in ovarian cancer using Spearman’s correlation analysis." (PMID 37684273, 2023). "Nevertheless, a recent study done to determine prognostic role of ELAVL1 in ovarian cancer found no significant role of ELAVL1 localization in determining the patient outcomes as well as its interaction with miR-200c." (PMID 27601996, 2016). "The results showed that the gene and protein expression patterns of ALKBH5, ELAVL1, and CDH2 were increased in ovarian cancer, while the protein expression of WTAP did not match the gene expression, suggesting gene transcription and translation may be involved in its preservation." (PMID 37684273, 2023). "Western blot showed that miR-519d transfection in ovarian carcinoma cells downregulated RhoC (Ras homolog gene family member C), Bcl-2, cyclin D1, survivin, MMP2, MMP9, STAT3 (signal transducer and activator of transcription 3), and HuR (ELAV-like RNA-binding protein 1) expression (P < 0.05)." (PMID 28146423, 2017).
cervical carcinoma (42 papers, 2008 to 2025). A carcinoma arising from either the exocervical squamous epithelium or the endocervical glandular epithelium. "For example, ELAVL1/HuR was reported to compete with miR-494 for the translation of nucleolin mRNA in cervical cancer cells." (PMID 38689093, 2024). "This competitive interaction between ELAVL1/HuR and miR-494 can partially affect cervical cancer cell proliferation by modulating nucleolin expression." (PMID 38689093, 2024). "Regarding its cooperative roles with miRNAs, ELAVL1/HuR can collaboratively function with let-7 to regulate c-Myc expression in cervical cancer cells." (PMID 38689093, 2024). "We identified seven genes consistent with prognosis and nine genes consistent with the process of cervical cancer formation, among which ELAVL1 and HSP90AA1 are involved in protein inter-righting." (PMID 35965520, 2022).
glioma (36 papers, 2012 to 2025). A benign or malignant brain and spinal cord tumor that arises from glial cells (astrocytes, oligodendrocytes, ependymal cells). "ELAVL1 is a well-known RNA-binding protein associated with multi-carcinogenesis, such as large cell lymphoma and glioma, by modulating RNA stability." (PMID 32170141, 2020). "ELAVL1, which is located on chr19p13.2, was reported to play critical roles in various tumors, including glioma, mainly by stabilizing target mRNAs upon binding." (PMID 38548861, 2024). "HUR (also named ELAVL1), an enriched protein, was highly expressed in glioma and negatively associated with patient prognosis." (PMID 35285415, 2022). "However, due to the heterogeneity between urothelial cancer and GBM the prediction value of ELAVL1 and its potential mechanism for immunotherapy still needs to be further proved by large glioma cohort treated by PD-1/L1 blockade." (PMID 33718217, 2021). "In addition, ELAVL1 may influence the efficacy of glioma heterogeneous targeted drugs by affecting cell fusion." (PMID 35711911, 2022). "In glioma, both in vitro and in vivo studies demonstrate that GACAT3 inhibits apoptosis by attenuating miR-3127-5p and consequently elevating ELAVL1 levels." (PMID 35127682, 2022). "In glioma, GACAT3 targets miR-3127-5p to downregulate ELAVL1 expression, thereby significantly enhancing cell proliferation and colony formation of A172 cells, U251 cells, and xenograft tumors." (PMID 35127682, 2022).
liver fibrosis (27 papers, 2016 to 2025). "Previous studies have reported an elevation in ELAVL1 level in human diabetic heart and implicated its role in cardiac pyroptosis, as well as ferroptosis in liver fibrosis." (PMID 33568052, 2021). "Recently, the RNA‐binding protein ELAVL1, also known as human antigen R, was found to be associated with ferroptosis in liver fibrosis." (PMID 34114349, 2021). "In mouse experiments, liver fibrosis production can be attenuated by iron death, for example, the RNA-binding protein, ELAVL1/HuR, plays a key role in regulating HSC ferroptosis and contributes to ferroptotic cell death." (PMID 40148434, 2025). "Specific knockdown of ELAVL1 in HSCs impaired sorafenib-induced ferroptosis of HSCs in murine liver fibrosis." (PMID 36703745, 2022). "Reportedly, NCOA4-mediated ferritinophagy can also contribute to ferroptosis through the RNA-binding protein ELAVL1/HuR pathway in liver fibrosis." (PMID 33632938, 2021). "Similar promoting role of ELAVL1 in ferroptosis has been reported during liver fibrosis, suggesting a conserved role of ELAVL1 in cell or tissue damage." (PMID 33568052, 2021). "Moreover, Beclin-1 mRNA has been shown as a target of ELAVL1 to trigger autophagy and ferroptosis in liver fibrosis." (PMID 33568052, 2021). "The precise function of ELAVL1 is unknown but it is believed to play a role in regulating ferroptosis in liver fibrosis." (PMID 33138772, 2020). "Zhang et al21 found that the up‐regulation of ELAVL1 was accompanied by increased levels of ferritinophagy and ferroptosis in human hepatic stellate cells and they propose that ELAVL1‐dependent ferroptosis may be a potential target in the treatment of liver fibrosis." (PMID 34114349, 2021). "The ELAVL1/HuR pathway also participates in NCOA4-mediated ferritinophagy, contributing to ferroptosis in liver fibrosis." (PMID 37950727, 2023). "The same research group further corroborated that manipulation of ferritinophagy is required for RNA-binding protein (ELAVL1/HuR or ZFP36) mediated ferroptotic bioactivity on HSC, conferring therapeutic target for the treatment of liver fibrosis." (PMID 32647111, 2020). "In this process, upregulated ELAVL1 binds to BECN1 mRNA and promotes BECN1/Beclin1 generation, resulting in autophagy-dependent degradation of ferritin, HSCs ferroptosis, and attenuated liver fibrosis." (PMID 36703745, 2022).